ACKR1 (atypical chemokine receptor 1 (Duffy blood group))
Diseases named in the same sentence as ACKR1 in open-access papers (continued):
Sharing a sentence is not in itself a finding about the gene and the disease.
tumor (continued). "Testing in either cell culture or the tumor xenografts showed that ACKR1 expression could prevent the spike of CCL2 and CXCL8 released into the growth media or tumor microenvironment." (PMID 37006247, 2023). "This suggests that ACKR1 is a general marker of venous endothelial cells rather than a tumor-specific endothelial cell marker." (PMID 37291214, 2023). "The sub‐clustering of ECs revealed six subtypes, including extra‐alveolar capillary EC (cEC) (FCN3+EDN1+PLVAP+), alveolar cEC (HPGD+EDNRB+IL1RL1+), arterial EC(GJA5+FBLN5+DKK2), lymphatic EC (CCL21+TFF3+FABP4), INSR+ tumour EC (INSRhiHSPG2+PLVAP+), and ACKR1+ tumour EC (ACKR1+SELP+IL1R1+)." (PMID 35184398, 2022). "Endothelial cells that highly expressed ACKR1 and PLVAP could enhance the transmigration of lymphocytes, and GRN was found to promote angiogenesis and tumor cell proliferation." (PMID 34805166, 2021). "Adhesional factors on the BBB endothelium such as ICAM-1, VCAM-1, or ACKR1 may be upregulated by IL-1β or IFN-γ, which can be delivered via convection-enhanced delivery (CED) directly to the tumor site." (PMID 34771532, 2021). "Resembling ACKR1 and many of the functions of ACKR2, ACKR4 demonstrates predominantly tumor-restricting effects, and was positively correlated with patient survival rates in several cancers; at times, ACKR4 expression was inversely correlated with the expression of chemokines in patient materials." (PMID 32582148, 2020). "We focus on ACKR1 (DARC), ACKR3 (CXCR7), CXCR4, and CCR2, as these are the best studied chemokine receptors in TEC; and suggest that targeting these receptors on the tumor vasculature may prove efficacious in slowing or reversing tumor growth." (PMID 30800123, 2019). "ACKR1 may act as a chemokine decoy receptor and interfere with normal tumor growth and chemokine-induced tumor neovascularization." (PMID 32456359, 2020). "Of utmost importance, with regard to ancestry and Fy- individuals, we have now begun to uncover variation in DARC/ACKR1 isoform levels in distinct tissues which may translate into variation of tissue-specific inflammatory responses, including those observed in the tumor microenvironment." (PMID 26473357, 2015). "Beyond ACKR1, the atypical receptor ACKR2, previously called D6, has been detected in tumor specimens, where it plays a negative role in tumor growth and metastasis." (PMID 30591657, 2018).
infection (58 papers, 2009 to 2026). The state of being infected such as from the introduction of a foreign agent such as serum, vaccine, antigenic substance or organism. "Using the inferred infection status and host genetic variation data, we sought to test for association between ACKR1 variation and Hepatocystis infection in this dataset." (PMID 40531971, 2025). "Some studies have proposed ACKR1 is involved in HIV interactions with erythrocytes that promote infection of other blood cells or maintain a viral reservoir." (PMID 37006247, 2023). "The N-terminus of ACKR1 is a recognition site for Plasmodium vivax and P. knowlesi, which invade erythrocytes during blood infection." (PMID 37006247, 2023). "Some people have naturally low ANCs without increased infection risk, caused by a homozygous T > C variant in ACKR1, commonly called the Duffy-null genotype." (PMID 42125771, 2026). "In skin diseases, it has been found that the interaction CXCL8/ACKR1 between macrophages and endothelial cells is enhanced, and the purpose of this interaction is to recruit immune cells to inflammatory sites in order to fight the infection." (PMID 37207221, 2023). "Interestingly, in addition to being an atypical chemokine receptor ACKR1/DARC (Duffy Antigen and Receptor for Chemokines) is the human blood group antigen and is also the receptor for infection of reticulocytes by the malarial parasite Plasmodium vivax." (PMID 28178200, 2017). "Absence of erythroid ACKR1 changes the steady-state hematopoiesis and may impact the bone marrow response during infection, inflammation, injury and cancer." (PMID 35547542, 2022).
cancer (39 papers, 2012 to 2025). A tumor composed of atypical neoplastic, often pleomorphic cells that invade other tissues. "EN0 showed higher expression of ACKR1 (logFC = 1.2), carcinoma-associated genes RACK1 (logFC = 0.7) and CD74 (logFC = 0.8)." (PMID 38328306, 2023). "Given the vital role that monocytes and inflammatory chemokines play in both CVD and cancer, common ACKR-1 polymorphisms would seem to be obvious candidates to modify the bidirectional risk between cardiovascular disease and cancer in AAs." (PMID 34733899, 2021). "DARC/ACKR1 has also been implicated to affect cancers as a pro-inflammatory cytokine receptor, specifically in lung cancer etiology, BrCa progression by in vitro studies and allele-specific BrCa patient survival." (PMID 26473357, 2015). "Naturally occurring variants were far more common than cancer-associated variants, with (cumulative) interface variant allele frequencies of ~31% (i.e., CCL24) and ~52% (i.e., ACKR1) for the most variable chemokines and receptors, respectively." (PMID 40273912, 2025). "A study found that CD82+ cancer cells have increased adherence to ACKR1+ vascular endothelial cells and suggested that a direct interaction leads to p21 cyclin-dependent kinase inhibition and prevention of metastatic escape." (PMID 37006247, 2023). "The mechanism of ACKR1 regulating pro-cancer chemokine signaling involves interplay between endothelial cells and erythrocytes that influences the activation of GPCRs CXCR2 and CXCR3." (PMID 37006247, 2023). "Another study injected mice with different cancer cell lines that expressed high or low levels of ACKR1 levels to show that cancer invasiveness was inversely related to ACKR1 activity." (PMID 37006247, 2023). "This underscores the importance of elucidating ACKR1 chemokine-binding mechanisms and the impact on immune cell responses to tumors to take steps towards enhancement or reconstitution of ACKR1-mediated protection in cancer therapy." (PMID 37006247, 2023). "CXCR7, a member of the subgroup of atypical chemokine receptors (ACKRs) known also as ACKR3, opens the gate for discussion of atypical activities of additional ACKRs in cancer: ACKR1 (DARC, Duffy), ACKR2 (D6), and ACKR4 (CCRL1)." (PMID 32582148, 2020). "While these studies implicate DARC/ACKR1 in cancer processes, there are still lingering questions concerning how DARC/ACKR1 lends its chemokine binding capacity toward cancer progression." (PMID 26473357, 2015). "Also, CXCL signaling promotes leukocyte infiltration in various cancer types through its interaction with ACKR1 in TECs." (PMID 38182557, 2024). "For example, nearly all adhesion/ECM signaling nodes involving either cancer luminal A cells, differentiated PVLs, or macrophages were enriched in the older cohort, while those involving iCAFs, myCAFs, and ACKR1+ endothelial cells were mostly enriched in the younger cohort." (PMID 39483921, 2024). "ACKR1 may play a role in fine-tuning the complex chemokine patterns that are hijacked by migrating cancer cells." (PMID 37006247, 2023). "Until then, ACKR1 may be used as a prognostic indicator for the aggressiveness of different cancer types and may be inform treatment regimens for patients with different patterns of ACKR1 expression." (PMID 37006247, 2023). "ER+ tumors are characterized by changes in the stromal compartment, with enrichment of endothelial cells (endo ACKR1, CXCL12, RGS5) and depletion of cancer-associated fibroblasts (iCAFs2 and myCAFs4), inflammatory monocytes (Mon S100A9), and B naive cells, compared with TNBC." (PMID 37549298, 2023). "Additionally, animal models, cancer cell experiments, ACKR1 biochemistry, and meta-analysis of clinical cohorts all indicate ACKR1 activity impedes cancer progression." (PMID 37006247, 2023). "Published and preliminary data in humans and mice genetically deficient in ACKR1 suggest that this common gene mutation may contribute to ethnic susceptibility to obesity-related disease, CVD, and cancer." (PMID 34733899, 2021).
cancer (continued). "Thus, to broaden the scope of atypical activities of chemokine receptors in cancer, a section of the review is dedicated to atypical roles of additional members of the ACKRs sub-group in malignancy: ACKR1, ACKR2, and ACKR4." (PMID 32582148, 2020). "Additionally, blood typing to discern ACKR1 phenotype could be an effective, low-cost way to inform cancer treatment." (PMID 37006247, 2023). "Atypical chemokine receptor 1 (ACKR1), previously known as the Duffy antigen receptor for chemokines (DARC), is a key regulator that binds chemokines involved in inflammatory responses and cancer proliferation, angiogenesis, and metastasis." (PMID 37006247, 2023). "Additionally, the interactions between chemokines, including CXCL1, CXCL8, and CCL2, and ACKR1, expressed by endothelial cells, were notably greater in MHC-II+ cancer cells than in MHC-II− cancer cells." (PMID 41281745, 2025). "ACKR1 and the ACKR subfamily may balance chemokine abundance and patterning to benefit host immune cell recruitment that is lost in unregulated, aggressive cancer types." (PMID 37006247, 2023). "The identified membrane proteins serve as receptors (EPHB6, ACKR1, and EDNRB) or adhesion molecules (EPCAM) and may enhance antitumor immunity (TENM2 and CLEC‐10A); thus, they may contribute to enhanced mEHT‐induced cancer destruction through regulating the TME related immune response." (PMID 38217262, 2024).
infectious disease (3 papers, 2010 to 2019). A disorder directly resulting from the presence and activity of a microbial, viral, or parasitic agent in humans. "A role for ACKR1 was also found in infectious diseases: it is the receptor for the human malarial parasites Plasmodium vivax and Plasmodium knowlesi and individuals lacking ACKR1 (Duffy negative), or carrying polymorphic variants, are less susceptible to P. vivax infection." (PMID 27375622, 2016).
neurodegenerative disease (2 papers, 2017 to 2023). A disorder of the central nervous system characterized by gradual and progressive loss of neural tissue and neurologic function. "Therefore, further research is needed on ACKR1–3 and CCRL2 in connection to neurodegenerative diseases." (PMID 38003682, 2023).
ACKR1 also shares sentences with these, for which no sentence is quoted: Plasmodium vivax malaria (10 papers); prostate carcinoma (7); viral infection (6); HIV-1 infection (5); parasitemia (5); asthma (3); genital herpes (3); glaucoma (3); liver cirrhosis (3); AIDS (2); bacterial infection (2); breast tumor (2); Cirrhosis (2); colon cancer (2); colorectal cancer (2); falciparum malaria (2); influenza (2); lung fibrosis (2); myasthenia gravis (2); neurological disease (2); sickle cell anaemia (2); thalassemia (2); triple-negative breast carcinoma (2); acute renal failure (1); adenocarcinoma (1); age-related macular degeneration (1); alcohol (1); Arthritis (1); brain cancer (1); breast adenocarcinoma (1).
A further 46 diseases each share a sentence with ACKR1 in 1 paper.